FZD3 (frizzled class receptor 3)
Description:
Receptor for Wnt proteins. Most of frizzled receptors are coupled to the beta-catenin canonical signaling pathway, which leads to the activation of disheveled proteins, inhibition of GSK-3 kinase, nuclear accumulation of beta-catenin and activation of Wnt target genes. A second signaling pathway involving PKC and calcium fluxes has been seen for some family members, but it is not yet clear if it represents a distinct pathway or if it can be integrated in the canonical pathway, as PKC seems to be required for Wnt-mediated inactivation of GSK-3 kinase. Both pathways seem to involve interactions with G proteins. Activation by Wnt5A stimulates PKC activity via a G protein-dependent mechanism. Involved in transduction and intercellular transmission of polarity information during tissue morphogenesis and/or in differentiated tissues. Plays a role in controlling early axon growth and guidance processes necessary for the formation of a subset of central and peripheral major fiber tracts. Required for the development of major fiber tracts in the central nervous system, including: the anterior commissure, the corpus callosum, the thalamocortical, corticothalamic and nigrostriatal tracts, the corticospinal tract, the fasciculus retroflexus, the mammillothalamic tract, the medial lemniscus, and ascending fiber tracts from the spinal cord to the brain. In the peripheral nervous system, controls axon growth in distinct populations of cranial and spinal motor neurons, including the facial branchimotor nerve, the hypoglossal nerve, the phrenic nerve, and motor nerves innervating dorsal limbs. Involved in the migration of cranial neural crest cells. May also be implicated in the transmission of sensory information from the trunk and limbs to the brain. Controls commissural sensory axons guidance after midline crossing along the anterior-posterior axis in the developing spinal cord in a Wnt-dependent signaling pathway. Together with FZD6, is involved in the neural tube closure and plays a role in the regulation of the establishment of planar cell polarity (PCP), particularly in the orientation of asymmetric bundles of stereocilia on the apical faces of a subset of auditory and vestibular sensory cells located in the inner ear. Promotes neurogenesis by maintaining sympathetic neuroblasts within the cell cycle in a beta-catenin-dependent manner (By similarity).
Synonyms: Fz-3
Tractability: Antibody: its Gene Ontology location is reachable by antibodies, with high confidence; UniProt places it where antibodies can reach, with medium confidence; UniProt predicts a signal peptide or a membrane-spanning region. PROTAC: UniProt records ubiquitination sites on it; ubiquitination databases record sites on it; its protein half-life has been measured.
Gene: Protein-coding gene on chromosome 8 (28,494,205 to 28,574,267, forward strand). Ensembl gene ENSG00000104290.
Subcellular location: Membrane; Cell membrane; Cell surface; Apical cell membrane
Subcellular location (Human Protein Atlas): Nucleoplasm; Nuclear membrane; Vesicles
Pathways (Reactome):
Signal Transduction: Asymmetric localization of PCP proteins; Ca2+ pathway; Class B/2 (Secretin family receptors); PCP/CE pathway
Gene Ontology:
Molecular function: PDZ domain binding; protein binding; Wnt-protein binding; Wnt receptor activity; transmembrane signaling receptor activity
Biological process: canonical Wnt signaling pathway; dopaminergic neuron axon guidance; midbrain morphogenesis; negative regulation of execution phase of apoptosis; negative regulation of mitotic cell cycle, embryonic; neuron differentiation; non-canonical Wnt signaling pathway; positive regulation of neuroblast proliferation; serotonergic neuron axon guidance; sympathetic ganglion development; Wnt signaling pathway, planar cell polarity pathway; cell surface receptor signaling pathway; hair follicle development; response to electrical stimulus; response to xenobiotic stimulus
Cellular component: cytoplasm; plasma membrane; apical plasma membrane; cell surface; apical part of cell; axon; dendrite; filopodium tip; glutamatergic synapse; lateral plasma membrane; membrane; neuronal cell body; presynaptic active zone; presynaptic active zone membrane
Genetic constraint (gnomAD): Loss-of-function variants: 13 observed, 40.22 expected, observed/expected ratio (o/e) 0.32, 90% interval 0.21 to 0.51. The upper end of that interval is the gene's LOEUF score, 0.51, which puts it in group 2 of 6, group 1 being the genes least tolerant of losing a copy. Missense variants: 409 observed, 603.01 expected, observed/expected ratio (o/e) 0.68, 90% interval 0.62 to 0.74. Synonymous variants: 188 observed, 213.52 expected, observed/expected ratio (o/e) 0.88, 90% interval 0.78 to 0.99.
Homologues: Orthologues: chimpanzee FZD3 (100% identical), macaque FZD3 (99% identical), dog FZD3 (98% identical), mouse Fzd3 (98% identical), pig FZD3 (98% identical), rat Fzd3 (98% identical), guinea pig FZD3 (96% identical), rabbit FZD3 (90% identical), tropical clawed frog fzd3 (90% identical), zebrafish fzd3a (76% identical), zebrafish fzd3b (76% identical), Drosophila melanogaster fz3 (20% identical). Paralogues in human: FZD6 (52% identical), FZD1 (37% identical), FZD7 (37% identical), FZD2 (36% identical), FZD5 (32% identical), FZD8 (31% identical), FZD10 (31% identical), FZD9 (30% identical), FZD4 (27% identical), SMO (24% identical), SFRP4 (14% identical), FRZB (12% identical), and 3 more.
Diseases named in the same sentence as FZD3 in open-access papers:
FZD3 is named in the same sentence as 72 diseases in open-access papers, as found by Europe PMC text mining. Sharing a sentence is not in itself a finding about the gene and the disease. The quoted sentences say what the papers report.
breast cancer (16 papers, 2013 to 2024). A primary or metastatic malignant neoplasm involving the breast. "5′-tiRNA-Val is a potential diagnostic biomarker for breast cancer, which is a new tumor suppressor through inhibition of the FZD3/Wnt/β-Catenin signaling pathway." (PMID 33860037, 2021). "Further research revealed that 5′-tiRNA-Val inhibits the FZD3/Wnt/β-catenin signaling pathway and becomes a new tumor suppressor, which may become a potential diagnostic biomarker for breast cancer." (PMID 38443680, 2024). "Concerning miRNA-FZD3, one report has been published about breast cancer and knockdown of FZD3 decreased MDA-MB-231 cell invasion." (PMID 34157951, 2021). "A latest study found 5′-tiRNA-Val was significantly low expression in breast cancer and it suppressed Wnt/β-catenin signaling pathway through directly targeting FZD3 mRNA 3′-UTR in breast cancer cells." (PMID 34225773, 2021). "Lately, 5′-tiRNA-Val has been proved to inhibit Wnt/β-catenin signaling pathway through targeting FZD3 mRNA 3′-UTR in breast cancer cells." (PMID 34225773, 2021). "A recent study revealed that the FZD3-mediated Wnt/β-Catenin signaling pathway was activated in breast cancer cells." (PMID 32174831, 2020). "The tRNAVal tiRNA targets Frizzled homolog 3 (FZD3) mRNA in a seed-dependent manner in human breast cancer cells." (PMID 31752361, 2019). "MiR‐31 regulates FZD3, a Wnt5A receptor, in the context of breast cancer invasiveness, and we observed that FZD3 mRNA was also downregulated upon miR‐31 transfection in ASCs." (PMID 27146333, 2016). "Furthermore, in breast cancer cells, 5ʹ-tiRNAval inhibited the FZD3-mediated Wnt/β-Catenin signalling pathway." (PMID 37480078, 2023). "FZD3 was validated as a direct target of 5ʹ-tiRNAval in breast cancer." (PMID 37480078, 2023). "This was the first study to identify 5ʹ-tiRNAval as a novel tumour suppressor that acts through inhibition of FZD3/Wnt/β-Catenin signalling, which could be a potential therapeutic target in breast cancer." (PMID 37480078, 2023). "Moreover, a study proved for the first time that by binding with its direct target (FZD3), 5′‐tiRNAVal could inhibit the Wnt/β‐catenin signalling pathway to suppress the cell proliferation and metastasis of breast cancer." (PMID 33507586, 2021). "5'-tiRNAVal expressed significantly low in breast cancer tissues and inhibited the translation of FZD3 by directly targeting the 3'-UTR of the human Frizzled homolog 3 (FZD3)." (PMID 38370372, 2024). "Downregulation of FZD3 inhibits the wingless-type MMTV integration site family (Wnt)/β-catenin pathway and thereby inhibits breast cancer progression and invasion, indicating potential tumor suppressor activities of tiRNAVal." (PMID 31752361, 2019). "These known targets included CEBPα, STK40, and E2F2 which had been shown to be downregulated at mRNA level by miR-31-H in ovarian cancer cells and Frizzled3 (Fzd3) and MMP16 which were repressed at the protein level by miR-31 in MDA-MB-231 breast cancer cells." (PMID 23472152, 2013).
melanoma (13 papers, 2008 to 2025). A malignant, usually aggressive tumor composed of atypical, neoplastic melanocytes. "In both melanoma and non-melanoma cancer cell lines, FZD3 is also overexpressed, and binding of WNT5 causes the cell to project and migrate." (PMID 34604862, 2021). "FZD3 has been found to be associated with β-catenin-independent-signaling and upregulation of this receptor is associated with melanoma progression and a reduced patient survival, whereas down-regulation of FZD3 suppresses growth and metastasis of melanoma." (PMID 32659938, 2020). "Moreover, the clinical association of FZD3 expression with melanoma progression and reduced patient survival has been observed." (PMID 39611156, 2024). "Finally, we noticed a strong correlation between WNT receptor Frizzled 3 (FZD3) expression and 9p loss in melanoma." (PMID 28749946, 2017). "Suppression of FZD3 expression reduces melanoma cell proliferation, colony formation, and invasiveness, inhibiting tumor initiation and growth in vivo." (PMID 40806546, 2025). "As previously reported, FZD3 is oncogenic in melanoma; high expression of FZD3 is correlated with poor OS in melanoma patients." (PMID 39052013, 2024). "Downregulation of FZD3 diminished the growth, colony-forming potential and invasive ability of melanoma cells, besides, the inhibition of FZD3 expression suppressed melanoma initiation and growth in vivo." (PMID 39611156, 2024). "It was established that FZD3 is essential for melanoma oncogenesis and establishes a positive feedback mechanism for activating the MAPK signaling network by initiating the non-canonical WNT pathway." (PMID 39611156, 2024). "It will be interesting to dissect the mechanistic difference between FZD3 and FZD6 in melanoma, as they clearly regulate different aspects of melanoma cell behaviors (FZD3 in cell proliferation and FZD6 in cell invasion)." (PMID 36620565, 2022). "Knockdown of FZD3 in patient-derived melanoma cells reduces melanoma cell proliferation and progression when engrafted into NSG mice." (PMID 36620565, 2022). "Overexpressed FZD3 has been detected in 20% of melanoma patients whose tumors were deprived of infiltrating T cells indicating the importance of this receptor in immune evasion." (PMID 32659938, 2020). "Along with FOXD1 and ATF3, CREB5 formed a transcription factor regulatory network that negatively regulates MAPK signalling, which is suppressed by FZD3 in melanoma." (PMID 32843066, 2020). "Modification of Wnt pathway modulators in melanoma cells, including Wnt5a, Wnt7b, Wnt10b, Frizzled-3 (FZD3) and DKKs has been largely investigated as a cell autonomous mechanism responsible of signaling activation in tumor cells." (PMID 33212834, 2020). "FZD3 is overexpressed in ~20% of human patient melanoma samples." (PMID 36620565, 2022). "On the other hand, knocking down fzd3 could inhibit the growth and metastasis of melanoma cells." (PMID 39452097, 2024). "Therefore, FZD3 blocking agents may enhance the efficacy of melanoma treatment when used in combination with available kinase inhibitors and immunotherapy." (PMID 32659938, 2020). "Moreover, it has been observed that FZD3 effectively modulates the activity of the mitogen-activated protein kinase/extracellular signal-regulated kinase (MAPK/ERK) pathway that is critical for melanoma maintenance." (PMID 32659938, 2020). "Although known at a descriptive level, FZD3, FZD7, and the most recent addition of FZD6 are involved in melanoma cell survival and invasion." (PMID 36620565, 2022). "For example, Frizzled-3 (FZD3) has been shown to be essential for melanoma oncogenesis by non-canonically initiating Wnt-MAPK signaling." (PMID 40806546, 2025).
melanoma (continued). "Both FZD3 and FZD6 have been found to play a pro-cancer role in melanoma." (PMID 36620565, 2022).
colorectal cancer (11 papers, 2008 to 2024). A primary or metastatic malignant neoplasm that affects the colon or rectum. "FZD3 protein expression has close association with the progression of colorectal cancer." (PMID 33832493, 2021). "A study assessing its clinical significance in colorectal cancer concluded that FZD3 was not only associated with carcinogenesis and progression; but also, its staining could be used as prognostic marker." (PMID 30704472, 2019). "FZD3 is highly correlated with colorectal cancer progression and its increased expression is reported in IBD colon tissue samples." (PMID 38353316, 2024). "FZD3 is tumorigenic in colorectal cancer development, as 75% of colorectal polyps, 89% of colorectal adenomas, and 100% of colorectal cancer specimens expressed FZD3." (PMID 34604862, 2021). "Specifically, we found that a subgroup of seven genes – BIRC5, CYCS, FZD3, FZD8, MAPK9, SMAD3, and SOS1 – that belong to the KEGG colorectal cancer pathway showed significant association with risk of BCC." (PMID 27367190, 2016). "To determine whether this induction pattern is sustained throughout tumorigenesis, we performed real-time RT–PCR analysis of NKD1 and FZD3 in a series of 23 colorectal cancers." (PMID 18414471, 2008). "Moreover, this provides evidence that miR-98-5p may inhibit the expression of FZD3, which may lead to reduced proliferation and metastasis of colorectal cancer cells, and these findings can be used in the development of target-based therapies for CRC patients." (PMID 37466730, 2023). "Another interesting finding from this study is that the median ICC score of the CAD associated with synchronous colorectal carcinomas is much higher than that of the group consisting of pure CAD, suggesting that a high FZD3 protein expression in CAD may signify a higher malignancy potential." (PMID 24255701, 2013). "As for miRNA-targeted genes in COAD, TUBB6, FZD3, and SERPINE1 were reported to be prognostic biomarkers in colorectal cancer potentially." (PMID 32964043, 2020).
schizophrenia (8 papers, 2008 to 2024). A major psychotic disorder characterized by abnormalities in the perception or expression of reality. "These include: VAT‐1, DAD‐1, PAQR9, BCKD, BDH, Prickle4, PP2A, RPL13A, SPRED2, KLP, FAM36A, NAB1, CLSTN3, PEDF‐R, and FZD3 (Frizzled gene previously associated with different psychopathologies, most notably Schizophrenia)." (PMID 27696737, 2017). "Studies in the last decade focused on the association between SNPs of the human Frizzled 3 gene (FZD3) and schizophrenia." (PMID 24403877, 2013). "In 2003, we reported a significant association between the gene encoding Fzd3 (FZD3) and susceptibility to schizophrenia." (PMID 18702828, 2008). "This hypothesis may be supported by our present and previous findings because the FZD3 gene was significantly associated with not only schizophrenia but also methamphetamine psychosis." (PMID 18702828, 2008). "Regulation of DNMT3A depends on miR-29 expression pattern in postnatal brain during lifespan so that downregulation of miR-29 associated with increased CH methylation in genes such as CHL1, FZD3, and SOX5 which are associated with schizophrenia." (PMID 38705955, 2024). "Emerging evidences suggest that FZD3 involves in the nosogeny of cancer and neuropsychiatric disorders, and especially participates functionally or genetically in schizophrenia." (PMID 33221742, 2020). "Researcher found that the frizzled-3 gene (FZD3), which encodes a receptor for Wnt ligands, was associated with schizophrenia in 3 different samples." (PMID 20492734, 2010). "The inconsistencies in genetic studies in the relationship of the FZD3 gene with schizophrenia may suggest heterogeneity of schizophrenia and a requirement for further studies using larger sample size." (PMID 18702828, 2008). "We consider that it may be also useful to investigate the role of the FZD3 gene in other types of psychotic disorders for better understanding of the physiological roles of Fzd3 and the Wnt cascade in schizophrenia or psychotic conditions." (PMID 18702828, 2008). "However, a study in Caucasians, which investigated the SNP rs960914, did not confirm the FZD3 as a risk locus for schizophrenia." (PMID 24403877, 2013). "This may imply that Fzd3 is involved in a liability to psychotic symptoms such as hallucination and delusion irrespective of whether they are due to schizophrenia or methamphetamine psychosis." (PMID 18702828, 2008).
chronic lymphocytic leukemia (4 papers, 2019 to 2023). "miR-607 downregulates Fzd3 expression, leading to inhibited Wnt/β-catenin signaling, which decreases chronic lymphocytic leukemia (CLL) progression and induces apoptosis." (PMID 34671643, 2021). "Further studies revealed that circ-CBFB acts as a sponge for miR-607 to reduce its levels, promote expression of the FZD3 target gene, and promote the activation of the Wnt/β-catenin pathway and subsequent progression of chronic lymphocytic leukemia." (PMID 31781492, 2019). "Additionally, the suppressive effect of miR-607 on the proliferation and apoptosis in chronic lymphocytic leukemia by targeting frizzled class receptor 3 has been confirmed." (PMID 34222137, 2021). "It has been shown that in B-cells of Chronic Lymphocytic Leukemia (CLL), mRNA related to Wnt elements is overexpressed, such as WNT3, WNT5B, WNT6, WNT10A, WNT14, WNT16 or FZD3." (PMID 37237497, 2023). "In chronic lymphocytic leukemia (CLL) cells, circ-CBFB indirectly upregulates Fzd3 expression and downstream Wnt/β-catenin signaling by inhibiting miR-607." (PMID 34671643, 2021).
colon cancer (4 papers, 2008 to 2025). "While FZD3 overexpression was associated with malignancies like lung cancer, FZD4 and FZD10 upregulation was frequently observed in pancreatic and colon cancer, respectively." (PMID 38906870, 2024). "Among the 14 model genes, the expression levels of FZD3, CDC25C, CDCA2, NEBL, and HMMR were positively correlated with better prognosis of colon cancer." (PMID 41425852, 2025). "In colon cancer, WNT2 might bind to FZD3 to upregulate AXIN2, as well as RNF43 for its negative feedback regulation, in which the modification and degradation of β-catenin are key pathway events in tumor progression." (PMID 39228892, 2024).
lung carcinoma (4 papers, 2011 to 2024). "In summary, the let-7f, as a major tumor suppressor regulatory factor, can exert its role in lung cancer via direct targeting genes such as HMGA2, SMARCAD-1, ARID-3, and FZD3 and can affect important processes, e.g. viability and proliferation of cancer cells." (PMID 35488374, 2022).
pancreatic cancer (4 papers, 2008 to 2025). "In pancreatic cancer, overall survival (OS) of patients with high FZD3 expression was better than that of patients with low FZD3 expression." (PMID 41425852, 2025).